CCL5 (C-C motif chemokine ligand 5)
Diseases named in the same sentence as CCL5 in open-access papers (continued):
Sharing a sentence is not in itself a finding about the gene and the disease.
infection (continued). "The levels of mRNAs for chemokines Ccl2, Ccl5, and Cxcl10 remained higher at 6 days after infection in spinal cords of Y114A-infected than WT-infected mice (P < 0.0001)." (PMID 32047134, 2020). "The four principal responses to mOVA2 infection of DCs in vitro, IFNα/β, CCL5, CXCL10, and IFNγ evident in the OT-I assay, also occurred in vivo." (PMID 31988324, 2020). "In the spinal cord, WT-infected mice had higher levels of Il6, Tnf, Ccl2, and Ccl5 mRNAs at 2 or 4 days after infection, while Il1β was highest in Y114A at 2 and 6 days (P < 0.01 versus G32S, P < 0.0001 versus Y114A)." (PMID 32047134, 2020). "The hMPV-infection of epithelial cells from the lung causes the secretion of the chemokines IL-8 (CXCL8) and CCL5 (RANTES)." (PMID 32545470, 2020). "Our results showed that Hypr infection of HBCA induced increased production of numerous cytokines/chemokines—particularly CCL5 (RANTES), CXCL10, IL-6, and IL-8, which confirmed our previous findings." (PMID 31699097, 2019). "In the late phases between 5 and 7 days post-infection, the inhibition of cytokines, except for IL-6 and CCL-5, was minor." (PMID 31293574, 2019). "Then we further demonstrated that autophagy blocked the production of the cytokines IL-8, CCL4, and CCL5 induced by SH0165 infection through the inhibition of NF-κB, p38, and JNK MAPK signaling pathway." (PMID 31106159, 2019). "The protein levels of CCL2, CCL3, CCL4, and CCL5 in the liver of μMT mice 6 weeks after infection were significantly increased compared with those of WT mice." (PMID 31194740, 2019). "Although the kinetics of mRNA induction by P. gingivalis differed between individual genes, I-BET151 uniformly reduced IL8, IL1B, CCL2, and CCL5 expression at 4 and 24 h post-infection." (PMID 31114581, 2019). "Second, pDCs release chemokines such as CCL5 that recruit CCR5+ CD4+ T cells to the site of infection and thus facilitate the spread." (PMID 31708924, 2019). "Next, the inflammatory response in osteoblasts was investigated by the determination of CCL5 (RANTES) by ELISA after 24 h of infection." (PMID 30823631, 2019). "Regarding to the role of chemokines, has been reported that elevated concentrations of CCL3 and CCL5 at day one post-infection are consistent with recruitment of monocytes and lymphocytes into the mice lungs." (PMID 30936869, 2019). "The production of CCL5 is dependent on virus subtypes (higher for avian viruses than human viruses), indicating that infection with avian viruses promotes more robust γδ T cell infiltration." (PMID 31612153, 2019). "Various chemokine genes, responsible for the control and recruitment of immune cells to the site of infection (i.e., Ccl2, Ccl4, Ccl5, Ccl7, Ccl8, Ccl12, and Ccl19), were also significantly upregulated in the VACV-Wyeth infected brains on 4 d.p.i." (PMID 30759813, 2019). "In this paper we showed that macrophages lacking lincRNA-EPS exhibit increased expression of inflammatory cytokines such as TNF-α, IL-6, IL1-β, and CCL5 upon infection with L. monocytogenes." (PMID 32039056, 2019). "The TLR3 signal also causes an upregulation of TLR2, which participates in the expression of IL1β, IL6, CCL2, and CCL5 genes by primary C57BL/6 astrocytes following a TMEV-BeAn infection." (PMID 30669615, 2019). "Our work also highlights for the first time that virally-stimulated sEVs promote an anti-viral CCL5 response in surrounding bronchial epithelial cells after infection." (PMID 31497021, 2019). "In agreement with the IFNB1 findings, silencing of PSMB1 promoted the mRNA expression levels of TNFA and CCL5 after infection with IAV and VSV." (PMID 30682859, 2019). "Importance of these chemokines in the mobilization of Treg cells to the lungs was demonstrated by the administration of anti-CXCL12 and anti-CCL5 neutralizing antibodies to mice prior infection and treatment with MDP." (PMID 29445379, 2018).
infection (continued). "It has been reported that p38, as well as PI3K/Akt is required for CCL5 production in astrocytes following infection with HIV infection." (PMID 30001342, 2018). "CCL5 induces the recruitment of different leukocyte types, including T cells, monocytes/macrophages, eosinophils, and basophils to sites of injury and infection." (PMID 29772686, 2018). "Recently, higher chemokines levels including CCL5/RANTES and CCL8/MCP-2 were quantified in organs from resistant (BALB/c) compared to susceptible (TLR4-defective C3H/HeJ) mice 24 h post-infection." (PMID 29974037, 2018). "IL6, IFNB1, CXCL10, and CCL5 gene expression was significantly elevated in ATII cells following infection and was reduced by the addition of apocynin (except for IFNB1)." (PMID 30341336, 2018). "Infection of alveolar Mφ by virulent M. bovis induced greater transcription of several chemokines, e.g., chemokine (C-C motif) ligand 5 (CCL5) and chemokine (C-X-C motif) ligand 1 (CXCL1), than that induced by an attenuated isogenic strain." (PMID 29263113, 2018). "CCL2, CCL3, and CCL5 belonging to inflammatory chemokines, are produced in high concentrations during infection or injury and determine the migration of inflammatory leukocytes into the damaged area." (PMID 30480097, 2018). "The production of CXCL10, CCL4 and CCL5 was markedly increased by HAV (HM-175/18f) infection in the culture of primary human hepatocytes and HepG2 cells." (PMID 28744018, 2017). "cGAS-deficient cells are also impaired in their response to infection with the cytosolic DNA virus MVA, as measured by CCL5 mRNA induction." (PMID 28194029, 2017). "CCL5 is a chemokine that is secreted by mesothelial cells and is well-known for its role the recruitment of mononuclear cells during infection." (PMID 28542390, 2017). "NH1125B, as compared to NH1067B, induced IL-6 earlier during infection and induced greater levels of CCL5 and TNFα transcripts in the MDM of the 2 donors (#67 and #68) presented." (PMID 28877226, 2017). "CCL5, a chemokine, attracts immune and inflammatory cells to the site of infection and is secreted by a variety of immune cells, among them macrophages and non-immune cells such as epithelial cells." (PMID 28877226, 2017). "Several chemokines Ccl2, Ccl5 and Ccl6, and genes from the lymphocyte antigen 6 superfamily, Ly6a, Ly6e and Ly6f were found to be modulated only with V3000 infection in brain." (PMID 28446152, 2017). "MCP-1 (CCL2) as well as RANTES (CCL5) were elevated in cardiac tissue 7 days after infection and significantly declined in the chronic phase." (PMID 28352641, 2017). "As we have previously established that epithelial cells produce C–C motif chemokine ligand 5 (CCL5) in response to infection that drives DC recruitment, we investigated production of CCL5." (PMID 27559003, 2017). "Meanwhile, the mRNA expression of Ifnα, Ifnβ, Ifnγ, Tnfα, and selective chemokines (Cxcl1, Cxcl2, and Ccl5) by leukocytes was lower in the blood of Ddx25-Tg mice on day 1 post-infection." (PMID 28824886, 2017). "WT infection of PMA-treated THP-1 cells resulted in higher levels of CCL5 in the supernatant than did infection of NHDF or hAEC and higher levels of IL-6 than did infection of NHDF." (PMID 28270578, 2017). "Analysis of mRNA levels of IL-6 and other pro-inflammatory cytokines and chemokines at 2.5 h, 4 h and 8 h post infection (p.i.) revealed a moderate induction of IL-6, TNFα, CCL3 and CCL5 upon IV infection of Calu-3 cells." (PMID 28195157, 2017). "At the same time, U51A reduces CCL5 expression, resulting in a peak at 24 h post-infection and a subsequently drop." (PMID 29194419, 2017). "Increased accumulation of the chemokines chemokine (C motif) ligand 1 (Xcl1), chemokine (C-C motif) ligand 5 (Ccl5), and chemokine (C-C motif) ligand 19 (Ccl19) have been observed in infection." (PMID 28075380, 2017). "At several time points post infection, supernatants were collected and the concentrations of IL-6 and CCL5 determined by BioPlex assay." (PMID 28877226, 2017).
infection (continued). "Inflammatory factors, such as TNFα and chemokines including Ccl2, Ccl5, Ccl9 and Cxcl2, were upregulated in response to more than one type of infection, particularly L. m and VSV." (PMID 28088779, 2017). "Infection with T. gondii induced a robust secretion of CCL5, which was significantly reduced by A-740003 (P=0.0058)." (PMID 27559003, 2017). "Pro-inflammatory cytokines (IFN-γ, IL-18, IL-6, TNF-α) and chemokines (CCL2, CCL5, CCL7, CXCL1, CXCL10) were found to be increased in sera of ZIKV-infected mice, indicating that infection causes systemic inflammation." (PMID 27163257, 2016). "Preceding the influx CD3+CD8+ T-cells in this model was an increase in Th1-type chemoattractants CXCL9, CXCL10, CCL3 and CCL5 at peak primary infection." (PMID 27467505, 2016). "Expression of Il6 and Ccl5 declined after initial NTHi infection, whereas other cytokines showed sustained upregulation." (PMID 26611891, 2016). "Lentiviral infection of WT iOPN expression plasmid into OPN-deficient macrophages restored SeV-induced expression of IFN-β, CXCL10, Mx1 and CCL5 to the same level as that in WT macrophages." (PMID 27026194, 2016). "In contrast, all three IAV subtypes induced a relatively low expression of CCL-5 for 24 h post-infection, but this increased at later time points." (PMID 28127293, 2016). "This reduced reconstitution is in part functionally compensated by the infection of MC, which degranulate and release the chemokine CCL5 for recruiting the CD8+ T cells more efficiently to extralymphoid sites of infection." (PMID 27540380, 2016). "A time dependent upregulation of CXCL1, CXCL2, CXCL3, IL-8, and CCL5 after infection with EV30 was observed." (PMID 27313404, 2016). "The O175A and O265B reassortant viruses produced similar secretome profiles, and in both of these samples the levels of proinflammatory mediators TNF-α, CCL3, and CCL5 were lower than those resulting from WT PR8 infection." (PMID 27489273, 2016). "Altogether these results suggest that CD8+ T-cell-derived CCL5 plays a significant role in maintaining elevated numbers of CD4+ T cells in the skin long term following an infection." (PMID 27160938, 2016). "As well as participating in the innate immune response, CCL3 and CCL5 also function in cell-mediated adaptive immunity as they both attract T lymphocytes to sites of infection and they preferentially recruit T helper (Th) type 1 differentiated cells." (PMID 27479136, 2016). "We found that the chemokine diffusion coefficient and CCL5 threshold impacts infection dynamics very slightly (negatively and positively correlated, respective) when the clearance scenarios are included." (PMID 26913242, 2016). "The concentrations of CCL-5 in the CK/SD/w4 infection were up-regulated to fivefold at 24 hpi (P < 0.01), whereas CXCL-10 was increased up to sevenfold at 18 hpi (P < 0.01)." (PMID 27446066, 2016). "A robust induction of chemokines including RANTES (CCL5) and IP-10 was also observed one week after infection." (PMID 26134299, 2015). "The expression of chemokines CCL3, CCL4 and CCL5 was reported during the acute and chronic stages of infection by T. cruzi." (PMID 26599761, 2015). "Further chemokine gene expression studies in brains of ECM-susceptible mice confirmed that CXCL10, CXCL9 and CCL5 and to lesser extent CCL2, CCL7, CCL3, CCL4 and CXCL2 are upregulated during infection with P. berghei ANKA." (PMID 24476686, 2014). "A mouse study that exposed animals to C. difficile toxin A implicated CCL5 (and its receptor, CCR1) as an important mediator of acute intestinal inflammation during infection." (PMID 24643077, 2014). "In the early days of infection (that is, day 0 to day 14), Met-CCL5 treatment substantially increased survival rates of these infected mice compared to control protein-treated mice (that is, 80% versus 30% survival rates at day 14)." (PMID 25182681, 2014).
infection (continued). "In the present study, we examined the levels of TNF, IL-1β, IL-6, IL-8, and CCL5 in the supernatants of HTNV-infected HUVECs at 48 h post infection using ELISA." (PMID 24714064, 2014). "In contrast, there was a striking expression of the Th1-related chemokine receptor CCR5 in the ileum and liver of infected mice, as well as the chemokine ligands for this receptor CCL3 (MIP-1α), CCL4 (MIP-1β) and CCL5 (RANTES) at 8 days post infection." (PMID 25119429, 2014). "In this study, we found that changes in the expression levels of several chemokines (Ccl2, Ccl3 and Ccl5) mirrored those of NF-κB signaling (similarly peaking 32 days post-infection)." (PMID 25116007, 2014). "In contrast, we observed significantly less production of IL-12p40, IL-12p70, IL-1α, IL-1β, IL-17A, CXCL1, CCL2 and CCL5 in the lungs as the infection progressed." (PMID 25119981, 2014). "We also show that the expression levels of several chemokines regulated by NF-κB signaling (Ccl2, Ccl3 and Ccl5) were similarly elevated at early infection." (PMID 25116007, 2014). "There was significantly more CCL5/RANTES after adult secondary infection than after neonatal secondary infection (P < 0.01)." (PMID 24173217, 2014). "Addition of Bb induced up-regulation of transcript levels for all chemokines assessed, including CXCL1, CXCL2, CCL2, CCL3, CCL4, and CCL5 by MØs and DCs as early as 4h post-infection." (PMID 24367705, 2013). "Infection resulted in a substantial up-regulation of CCL5 which co-localized with CD31, an endothelial cell marker." (PMID 23516647, 2013). "Genetic analysis of F2 hybrids has revealed identical genetic control of serum levels of CCL3 and CCL5 at week 7 after infection." (PMID 23875032, 2013). "Levels of mRNAs for CCL2, CCL3L1, CCL4, CXCL10, CCR1 and CCR5 were significantly increased in at least one time point following infection in two experiments and CCL5, CCR9 and CXCR4 mRNA were significantly increased in one of the experiments." (PMID 24083897, 2013). "Those mRNAs for CCL2, CCL31, CCL4, CXCL10, CCR1 and CCR5 were significantly increased following infection in both experiments in at least one time-point and CCL5, CCR9 and CXCR4 mRNA were significantly altered in one of the experiments." (PMID 24083897, 2013). "At 7 and 14 dpi, lung CCL5 mRNA was significantly increased after infection, although the magnitude of induction was similar in mPGES‐1+/+ and mPGES-1-/- mice." (PMID 24147040, 2013). "These gene lists also featured a number of inflammatory cytokines and chemokines involved in chemotaxis of myeloid and lymphoid cell types to the sites of infection (Ccl4, Ccl5, Ccl7, Ccl12, Cxcl9, Cxcl10)." (PMID 23853600, 2013). "HCMV also encodes a miRNA, mir-UL148D, not expressed by laboratory strains of the virus, that can target CCL5 mRNA for degradation at late times post infection." (PMID 23202490, 2012). "One study showed that infection of mice with L. major upregulated the gene expression of several chemokines (RANTES/CCL5, MIP-1α/CCL3, IP-10/CXCL10, and MCP-1/CCL2) in cells collected from the footpad and their draining lymph nodes." (PMID 22131998, 2012). "Mast cell–derived cytokines and chemokines can enhance the migration of dendritic cells (DCs; TNF-α and CCL20) and effector T cells (CXCL10/IP10 and CCL5/RANTES) to the site of infection and to draining lymph nodes." (PMID 22577358, 2012). "Rather, RTD-1 administration appeared to protect infected animals by reducing pulmonary inflammation and suppressing IL-1α, IL-1β, IL-6, IL-12, CXCL1 (KC), CCL2 (MCP-1), CCL3 (MIP-1α), and CCL5 (RANTES) 2–4 days post-infection." (PMID 23236475, 2012). "CCL5/RANTES plays an important role in regulating the movements of inflammatory cells to the infection sites." (PMID 22330747, 2012). "A549 cells were infected with a multiplicity of infection (moi) of 0.013, 0.04 or 0.13 and supernatant levels of IL-6 and CCL5 were determined at 24 hours post-infection." (PMID 22962966, 2012).
infection (continued). "We confirmed the results found for CCL2 and CCL5 by ELISA and found higher concentrations of protein at 20 weeks of infection in lesions from TNFR1 KO mice." (PMID 22203861, 2012). "Inflammatory cytokines, such as IFNγ, interleukin (IL)-6 and TNFα, and the chemokines, CCL2 and CCL5, were highly upregulated in the respiratory tract after infection with 12500 EID50." (PMID 22496659, 2012). "Airway levels of CXCL1, CCL2, CCL3, CCL5, IFNγ, IL-6, and TNFα were measured 3 and 6 days after infection." (PMID 22496659, 2012). "We next determined the levels of the Ccr1 agonists Ccl3, Ccl5, Ccl6, Ccl7, Ccl8 and Ccl9 in Ccr1+/+ and Ccr1−/− kidneys after infection." (PMID 22916017, 2012). "CC-chemokine ligand 5 (CCL5) also known as RANTES specifically attracts and aids in the migration of the mononuclear macrophages and leukocytes to the site of infection." (PMID 22666564, 2012). "In the brain, its ligand CCL5 (RANTES) expression is highly upregulated during infection/inflammation, including WNV, MHV, HSV and tick-borne encephalitis virus encephalitides." (PMID 23244217, 2012). "Expressions of TLR3, IFNα, IL6, IL8 and CCL5 in the lungs following infection with the two HPAIVs were low." (PMID 21826229, 2011). "Poly(I-C) induction of genes involved in alerting the innate immune system to the infectious threat, including TNF-alpha, IL-1 alpha and beta, CCL5 and IL-6, were suppressed by infection with live MPV." (PMID 21267444, 2011). "Levels of IFNβ, CXCL10 and CCL5 are induced by infection at all time points but the response is impaired in LGP2-deficient cells compared to wild-type." (PMID 21533147, 2011). "Infection of the cells with HSV-2 or stimulation with the TLR9 ligand ODN1826 led to accumulation of CCL5 and IFN-α/β in the culture supernatants of the cells expressing AdV-vector and this response was significantly decreased in cells expressing Adv-Grx." (PMID 21949653, 2011). "To evaluate the expression of ISGs in response to C. pneumoniae infection, we harvested total RNA from cells receiving bacterial or mock infection for the indicated time intervals and looked for expression of CCL5, ISG56, and CXCL10." (PMID 20386592, 2010). "At 18 hours post-infection, IL-6, CCL-5/RANTES and CXCL-10/IP-10 were highly expressed (12 to >1000 folds) in H5N1/2004 infection." (PMID 21108843, 2010). "The highest level of induction (36 folds) for CCL-5/RANTES was observed at the late phase of H5N1/2004 infection (18-24 hours)." (PMID 21108843, 2010). "We also report here a small transient increase in CCL4 and CCL5 mRNA one day post L. major inoculation at the site of infection in C57BL/6 mice, but CCL3 clearly showed a much higher level of transcriptional induction in these mice." (PMID 20140197, 2010). "Even though we are focusing on the early response (8, 24 and 48 hpi) during the infection, the genes expressed differentially at day 21, include CCL5, CCR5, TGFB3 and AIF1, and provide additional gene profiling data during the chronic infection stage." (PMID 18811943, 2008). "Most importantly, chemokine genes e.g., Cxcl9, Cxcl10, Cxcl11, Cxcl13, Ccl3, Ccl5 and Ccl12 that exert a chemotactic signal for the immune cell migration to the site of the injury were upregulated at 72 and 96 hr post infection." (PMID 18558011, 2008). "The sharp IgA Ab response generated by Chlamydia-infected mice also correlated with the predominant Th1 >> Th2 cytokine response induced by this infection, which were reduced by CCL5 blockade." (PMID 18700040, 2008). "In mice infected with the ΔsigC mutant, the levels of TNF-α, IL-1β, IL-6 and IFN-γ began to drop 14 days post infection and persisted throughout the study while a significant reduction in CCL-2 and CCL-5 levels was detected 70 days after infection." (PMID 18798983, 2008). "These levels were significantly lower (p<0.005 for CCL3; p<0.05 for CCL4 and CCL5) than those prior to infection." (PMID 17684570, 2007).